SLC7A5 (solute carrier family 7 member 5)
Diseases named in the same sentence as SLC7A5 in open-access papers (continued):
Sharing a sentence is not in itself a finding about the gene and the disease.
colon carcinoma (13 papers, 2016 to 2025). "SLC1A4, SLC2A1, SLC3A2, SLC6A8, and SLC7A5 are transported as mRNAs by lung- and colon cancer-related exosomes." (PMID 41440381, 2025). "CPTAC database analysis showed that SLC7A5 protein was highly expressed in colon cancer, hepatocellular carcinoma, head and neck squamous carcinoma, lung adenocarcinoma, ovarian cancer and UCEC." (PMID 38790003, 2024). "In colon cancer, as a result of the strong driving force of Myc oncogene products, SLC7A5 was upregulated, which resulted in metabolic reprogramming associated with cancer development." (PMID 38790003, 2024). "In a xenograft model, antitumor activity against human colon cancer was mediated by anti-SLC7A5 monoclonal antibodies." (PMID 37404825, 2023). "We found that MYC promotes the import of tryptophan into colon cancer cells by transcriptionally driving the expression of SLC7A5 and SLC1A5, which are capable of transporting tryptophan." (PMID 31922097, 2020). "Silencing SLC1A5 or SLC7A5 in the colon cancer cell line HCT15 led to a reduction of 13C-Trp and 13C-Kyn observed 1 h after addition of 13C-Trp to the culture medium." (PMID 31416966, 2019). "Nevertheless, cultured colon cancer cell lines examined here had an increase in SLC7A5 and AFMID, indicating that the Kyn pathway is active." (PMID 31416966, 2019). "In the HT-29 colon carcinoma cell line, SLC7A5 transcription was 8-fold higher compared to K1 (used as basal level = 1), whereas in the prostate cancer cell line LNCaP, SLC7A5 transcripts were undetectable." (PMID 30241549, 2018). "According to the colon cancer Cox regression test and Kaplan–Meier (K-M) curves of key genetic risk factors, the five most significant genes selected were: ELAV-like RNA-binding protein 1 (ELAVL1), GPX2, EPAS1, SLC7A5, and high mobility group box 1 (HMGB1)." (PMID 36324584, 2022). "SLC7A5 was the most consistently up-regulated gene in the Trp pathway in cultured colon cancer cell lines, and Western blots confirmed that SLC7A5 protein was dramatically up-regulated in colon cancer cells, while changes in SLC1A5 were more modest." (PMID 31416966, 2019). "Elevated levels of the enzymes TDO2, IDO1, and AFMID combined with the Trp transporters SLC1A5 and SLC7A5 in colon cancer patients may lead to increased Trp and Kyn levels in colon cancer cells." (PMID 31416966, 2019). "Indeed, previous immunohistochemistry (IHC) studies found that both SLC1A5 and SLC7A5 were up-regulated in colon cancer cells." (PMID 31416966, 2019). "We identified five core genes, ELAVL1, GPX2, EPAS1, SLC7A5, and HMGB1, involved in the ferroptosis of colon cancer." (PMID 36324584, 2022). "Our results suggest that five core genes, ELAVL1, GPX2, EPAS1, SLC7A5, and HMGB1, are involved in the ferroptosis of colon cancer cells." (PMID 36324584, 2022). "SLC7A5, SLC1A5, and AFMID were elevated in colon cancer cells and tissues, and kynurenine was significantly greater in tumor samples than in the respective adjacent normal tissue from patients with colon cancer." (PMID 31416966, 2019). "To validate these results, we performed RT-qPCR for SLC1A5, SLC7A5, TPH1, TDO2, IDO1, AHR, and MYC in colon cancer and normal tissue of the same patients." (PMID 31416966, 2019). "Our results confirmed that SLC7A5, SLC1A5, TDO2, IDO1, and AHR were all elevated in colon cancer, while TPH1 was reduced." (PMID 31416966, 2019). "Interestingly, TCGA analysis demonstrated that most colon cancer samples have greater expression of the tryptophan transporters SLC1A5 and SLC7A5 and the enzyme AFMID than the normal tissues from the same patients." (PMID 31922097, 2020).
glioma (12 papers, 2019 to 2025). A benign or malignant brain and spinal cord tumor that arises from glial cells (astrocytes, oligodendrocytes, ependymal cells). "Comparing the two groups, we found that SLC7A5 (solute carrier family 7 member 5) expression was higher in gliomas with TERT promoter mutations." (PMID 40149633, 2025). "Additionally, our analysis of glioma transcriptomic data from the TCGA database revealed that gliomas with TERT promoter mutations exhibit higher expression levels of SLC7A5." (PMID 40149633, 2025). "Particularly, ECs from glioma exclusively expressed a series of transmembrane transport-associated genes, including SLC2A1, BSG, SLC7A1, and SLC7A5, suggesting that ECs in brain tumors were still involved in retaining the brain-blood barrier." (PMID 39345334, 2024). "LAT1/SLC7A5 has been in the spotlight of drug delivery efforts because it is abundant in BCECs of the BBB as well as in glioma cells and other tumors." (PMID 36770817, 2023). "In particular, LAT1/SLC7A5 has been used to deliver anticancer medication through the BBB for the treatment of glioma, either for imaging/detection/staging purposes or for developing anti-cancer therapeutics." (PMID 36770817, 2023). "The expression of L-Type amino acid transporter 1 (LAT1: SLC7A5) in human glioma correlates with MET uptake." (PMID 35326600, 2022). "The initial cloning of the major LNAA transporter, designated LAT1 (SLC7A5), from a C6 rat glioma line was enabled by the co-expression of 4F2hc (SLC3A2), which forms a hetero-duplex within the membrane with LAT1." (PMID 35745855, 2022). "Since LAT1 is the protein encoded by the SLC7A5 gene, we hypothesize that the higher TERT promoter mutation rate in neocortical gliomas may lead to increased LAT1 expression, which in turn enhances FET uptake and consequently increases metabolic activity." (PMID 40149633, 2025). "To validate our in vitro results, we assessed the expression of SLC3A2, SLC7A5, and ATB0,+ in tumors obtained from HGG13 glioma-implanted mice." (PMID 37349515, 2023). "Another SLC7A5-specific tracer, 18F-fluoro-phenylalaine (18F-FBPA), has low accumulation in the inflammatory regions and high uptake by tumor tissues in the glioma xenograft model." (PMID 33401748, 2021). "In the previous studies, miR-136-3p inhibits cell growth and metastasis by targeting solute carrier family 7 member 5 (SLC7A5) and ADAM metallopeptidase domain 9 (ADAM9) in thyroid cancer, suggesting that miR-136-3p might function as a tumor suppressor in cancers including gliomas." (PMID 32677950, 2020).
melanoma (12 papers, 2013 to 2025). A malignant, usually aggressive tumor composed of atypical, neoplastic melanocytes. "Carrier-mediated proteins overexpressed in melanoma cells include L-type amino acid transporter 1 (LAT1/SLC7A5), L-type amino acid transporter 2 (LAT2/SLC7A8), alanine-serine-cysteine transporter 2 (ASCT2/SLC1A5), and glucose uptake transporter 1 (GLUT1)." (PMID 31717859, 2019). "SLC7A5 expression is indicative of a poor prognosis in pancreas cancer, melanoma, bile duct adenocarcinomas, and clear cell renal cell carcinoma." (PMID 30558624, 2018). "Among them, only four miR-126&126* putative targets were shared by both melanomas being two of them, the solute carrier family 7, member 5 (SLC7A5) and ADAM9 (and this paper) already confirmed as direct targets of miR-126." (PMID 23437250, 2013). "However, this only has been validated at the mRNA level in a subset of breast tumours and melanoma cell lines, which showed however more than five times increase in SLC7A5 expression compared to SLC7A8." (PMID 32200487, 2020). "Our functional esiRNA screen identified five candidate translation targets of VARS (that is, HADH, KIF13B, SLC7A5, QDPR and GOLT1B), whose depletion re-sensitizes resistant melanoma cells to MAPK therapy." (PMID 38849541, 2024). "The genes of HAMP, SLC7A5, CYBB, and IFNG were highly expressed in melanoma cell lines, while JDP2, TUBE1, PROM2, GPX2, FBXW7, and ARNTL were lowly expressed in melanoma cell lines." (PMID 35373463, 2022). "In melanoma cells, enhanced SLC7A5 expression increased the uptake of essential amino acids and the subsequent maintenance of mTORC1 activity, and blocking the MAPK-c-MYC-SLC7A5 signaling axis effectively suppressed cancer cell growth." (PMID 38722983, 2024).
prostate carcinoma (10 papers, 2016 to 2025). A carcinoma that arises from epithelial cells of the prostate gland. "What is known is that some of these gene products were shown to be implicated in prostate cancer progression, such as, for example, SLC7A5, SLC7A11, SLC11A1, SLC43A1 and SLC1A3." (PMID 36831650, 2023). "Overexpression of LAT1 is also closely related to the proliferation of cancer cells, such as lymphoma, esophageal cancer, lung cancer, and prostate cancer cells, owing to the critical role of SLC7A5 in activating mTORC1 signaling and metastasis in tumors." (PMID 37545500, 2023). "SLC7A5/LAT1 was found overexpressed in a wide range of solid tumors including the most frequently diagnosed cancers such as breast cancer, prostate cancer, and lung cancer." (PMID 31100853, 2019). "In prostate cancer, expression of androgen receptor–mediated LAT3 (SLC43A1) and leucine uptake can be inhibited by anti-androgen treatment, inducing the compensatory upregulation of LAT1 (SLC7A5)." (PMID 33511116, 2020).
autism spectrum disorder (7 papers, 2018 to 2025). A spectrum of developmental disorders that includes autism, and Asperger syndrome. "Mutations in SLC7A5 that lead to the partial loss of transport activity have been found in patients with autism spectrum disorder, associated with a decrease in the brain levels of branched-chain amino acids." (PMID 34579098, 2021). "Consistently, pathogenic variants in SLC7A5 lead to autism spectrum disorders." (PMID 41116060, 2025). "As a proof-of-principle, we tested our approach on two novel CRISPR-generated mutant zebrafish lines carrying predicted null-alleles of syngap1b and slc7a5, orthologs to two human genes implicated in autism-spectrum disorder, intellectual disability, and epilepsy." (PMID 33330465, 2020). "Recently reported Slc7a5 mutations linked to autosomal recessive inherited neurodevelopmental delay/autism spectrum disorder (A246V and P375L) have attenuated effects on Kv1.2 gating and current density, possibly due to a localization defect that prevents association with Kv1.2." (PMID 30356053, 2018). "One of its human orthologs, SLC7A5, is an amino acid transporter, mutations in which are associated with autism spectrum disorder and defects in motor coordination." (PMID 31107875, 2019).
diabetes (7 papers, 2016 to 2024). "In our study, 6 out of 71 differentially expressed genes had records of SNPs associated with an increased risk of diabetes, including Uqcr10 and Slc7a5." (PMID 36557283, 2022). "Additionally, SNPs within SLC7A5 (rs76069656, rs4384608) were previously reported to link with an increased diabetes risk." (PMID 36557283, 2022). "It is also interesting to note that in elderly subjects the same allelic variants of SLC7A5-rs731710 and SLC7A8-rs3783436 were found associated with better physical performance, reported to be impaired in people with diabetes." (PMID 36364703, 2022). "In this respect, the marginal association of the allelic variants SLC7A5 rs731710-G and SLC7A8 rs3783436-C with a reduced risk of diabetes is a result that deserves some attention." (PMID 36364703, 2022). "One possible biomarker that may reflect changes in beta cell function during the development of diabetes is the large neutral amino acid transporter, LAT1 (SLC7A5)." (PMID 27909574, 2016).
pancreatic cancer (7 papers, 2018 to 2024). "In line with this, the SLC7A5 inhibitor JPH203 exhibited synergistic effects when combined with a KRAS G12D inhibitor in 3 pancreatic cancer cell lines carrying the KRAS G12D mutation." (PMID 39704172, 2024). "The prognostic significance of this gene has been illustrated by the association of high SLC7A5 expression with shorter overall survival in patients with pancreatic cancer." (PMID 33783998, 2021). "Importantly, a study revealed that c-Myc regulates SLC7A5 in pancreatic cancer, and inhibition of c-Myc leads to severe reduction of SLC7A5 protein level." (PMID 38705513, 2024). "SLC7A5 functions as an l-type amino-acid transporter that transports large neutral amino acids and is over-expressed in many cancer types, such as prostatic, esophageal, gastric, and pancreatic carcinomas." (PMID 30558624, 2018). "SLC7A5 and SLC3A2 expression is highly upregulated in many tumor types, such as HNSCC, prostate, lung, breast, and pancreatic cancers." (PMID 33401748, 2021). "Since c-MYC has been shown in the context of pancreatic cancer cells to drive SLC7A5 transcription, in our mouse model we have tested the relative role of the RAF-MEK-ERK and Pi3’K pathways for Slc7a5 transcription." (PMID 30241549, 2018).
psoriasis (7 papers, 2020 to 2025). An autoimmune condition characterized by red, well-delineated plaques with silvery scales that are usually on the extensor surfaces and scalp. "Accordingly, SLC7A5 has emerged as a promising novel strategy for cancer therapy and to control inflammatory and immunological disorders such as psoriasis, rheumatoid arthritis, or allergic diseases." (PMID 40399490, 2025). "Psoriasis-related compounds corresponding to SLC7A5 and SLC7A11 were also identified, including Melphalan, Quisqualate, Riluzole, and Sulfasalazine." (PMID 36276287, 2022). "JPH203 treatment and Slc7a5 gene disruption in CD4+ T cells alleviated disease progression with cytokine production in a psoriasis mouse model." (PMID 35454142, 2022). "Recent research indicates that SLC7A5 may influence ferroptosis pathways, potentially influencing the pathogenesis of psoriasis." (PMID 40729322, 2025). "Thus, our results indicate SLC7A5, SLC7A11, and CHAC1 as the underlying biomarkers for psoriasis, providing further evidence about the crucial role of ferroptosis in psoriasis." (PMID 36276287, 2022). "Interestingly, increased transcriptional levels of SLC7A5 were detected in skin samples of patients with psoriasis." (PMID 32715162, 2020). "Deletion of Slc7a5 in γδ and CD4 T cells reduced the psoriasis-like symptoms in imiquimod-treated mice." (PMID 41002986, 2025). "Similar to the results of paired samples in the GSE30999 dataset, the expression levels of SLC7A5, SLC7A11, and CHAC1 were increased in the psoriasis lesions (1.85-, 1.73- and 1.70-fold, respectively) compared to normal skin tissues." (PMID 36276287, 2022). "SLC7A5, SLC7A11, and CHAC1 may affect the development of psoriasis by regulating ferroptosis." (PMID 36276287, 2022).
thyroid cancer (7 papers, 2015 to 2020). "Further, SLC7A5 regulated by miR-126-3p exhibited a strong association with cellular migration and metastasis in thyroid cancer cells." (PMID 32867828, 2020). "S2) emphasizing the fact that SLC7A5 is associated with the most aggressive untreatable cases of thyroid cancers." (PMID 30241549, 2018). "Finally, the finding of high SLC7A5 levels significantly co-occurring with low SLC5A5 transcripts might indicate that LAT1 is associated with aggressive forms of thyroid cancer like RAI refractory PTC." (PMID 30241549, 2018). "We found that miR-126-3p overexpression significantly decreased luciferase activity as compared to the negative control, suggesting that miR-126-3p directly targets the 3′-UTR region of ADAM9 and SLC7A5 in thyroid cancer cells." (PMID 26244545, 2015). "SLC7A5 is overexpressed in various types of cancer, including thyroid cancer, and various levels of SLC7A5 overexpression have been associated with high-grade malignancies and poor prognoses." (PMID 26244545, 2015). "SLC7A5 transcripts were found in all 6 thyroid cancer cell lines tested with variable levels." (PMID 30241549, 2018). "The overexpression of SLC7A5 and SLC7A11 may be partly attributed to macrophages, and tumor-associated macrophages are activated and present in thyroid cancer microenvironment." (PMID 30558624, 2018). "This suggests that SLC7A5 and ADAM9 are two target genes among others that mediate the tumor suppressive effects of miR-126-3p on growth and migration in thyroid cancer cells." (PMID 26244545, 2015). "Screening the DCGs across 12 cancer types (bladder, breast, colon, esophagus, kidney, liver, lung, skin, ovary, prostate, sarcoma, and thyroid cancers), suggested that these genes could be speculated as metastatic-related genes as DCGs-shared GART and SLC7A5 with 12 tumor types." (PMID 29843204, 2019).
breast tumours (6 papers, 2018 to 2025). "SLC1A5, GLS, PYCR1 and PIK3CA were significantly expressed in breast tumours with high expression of SLC7A5 (p < 0.001), while the low expression of SLC7A5 was associated with high levels of p-mTORC1 (p < 0.001)." (PMID 29566741, 2018). "SLC7A5 protein expression was significantly expressed in breast tumours with high Ki67, and the upstream effector MYC (p < 0.001)." (PMID 29566741, 2018). "Apart from SLC7A8, all the following amino acid transporters, SLC7A5, SLC3A2, SLC7A11 and SLC38A2, were significantly expressed in breast tumours with high SLC1A5 expression (P < 0.01)." (PMID 39843491, 2025). "SLC7A5, SLC1A5, GLS and PIK3CA were significantly expressed in breast tumours with high expression of SLC3A2 (p < 0.001), while the low expression was associated with high levels of p-mTORC1 (p < 0.001)." (PMID 29545595, 2018).
endometrial carcinoma (6 papers, 2017 to 2025). A malignant tumor arising from the epithelium that lines the cavity of the uterine body. "Long non-coding (lnc) RNA OIP5-AS1 upregulates SLC7A5 via targeting miR-152-3p, resulting in increased leucine uptake, further promoting proliferation, migration and invasion of endometrial cancer cells." (PMID 37940982, 2023). "OIP5-AS1 can boost proliferation, migration, and invasion in endometrial carcinoma cells by sponging miR-152-3p to upregulate SLC7A5 expression since SLC7A5 is a target of miR-152-3p." (PMID 36499136, 2022). "CircZNF124 regulates the expression of SLC7A5 through binding to miR-199b-5p in endometrial cancer." (PMID 37940982, 2023). "Although there was no reports of OIP5-AS1 regulating SLC3A2/SLC7A5 in OA, study have demonstrated that in endometrial carcinoma cells, OIP5-AS1 can upregulate the expression of SLC7A5 by targeting miR-152-3p, thereby promoting cell proliferation." (PMID 40420260, 2025).
hepatocellular carcinoma (6 papers, 2018 to 2025). A malignant tumor that arises from hepatocytes. "It has been shown that YAP1 and TAZ bind directly to the SLC7A5 promoter to upregulate its transcription and inhibition of SLC7A5 blocks YAP1/TAZ-mediated tumorigenesis of hepatocellular carcinoma." (PMID 33953707, 2021). "In hepatocellular carcinoma, previous study proved that YAP1/TAZ activated the mTORC1 pathway via up- regulating amino acid transporters (SLC38A1 and SLC7A5) to promote cell growth." (PMID 32003757, 2020). "The mRNA expression levels of SLC7A5 and GLS were significantly decreased after treatment with JHU083, which demonstrated the successful inhibition of glutamine metabolism in subcutaneous hepatocellular carcinoma tumor tissue." (PMID 36497182, 2022).